LECT2 (leukocyte cell derived chemotaxin 2)
Diseases named in the same sentence as LECT2 in open-access papers (continued):
Sharing a sentence is not in itself a finding about the gene and the disease.
metabolic syndrome (continued). "In addition, it has been suggested that the association of LECT2 with abdominal obesity and lipid metabolism may influence its relationship observed with both MASLD and metabolic syndrome." (PMID 39409124, 2024). "LECT2 is not a routine diagnostic marker for any disease, but it has been associated with many pathologies, including systemic amyloidosis, rheumatoid arthritis, diabetes, atherosclerosis, and metabolic syndrome." (PMID 38137613, 2023). "Because it has been confirmed that activation of liver AMPK enhances fatty acid oxidation and inhibits triglycerides and cholesterol synthesis, LECT2 may play a role in visceral fat-induced inactivation of liver AMPK, and therefore be associated with dyslipidemia." (PMID 28278265, 2017). "Furthermore, the lack of association between VFA and dyslipidemia after adjustment for LECT2 suggests that the relationship between VFA and dyslipidemia is partially mediated by LECT2." (PMID 28278265, 2017). "As a result, LECT2 concentrations in the subjects with metabolic syndrome were significantly higher than the subjects without metabolic syndrome (32.6 [17.8, 45.0] vs. 27.0 [18.7, 33.7] ng/ml, P = 0.016)." (PMID 28376109, 2017). "Additionally, the correlation between plasma LECT2 levels and VFA was examined when the participants were stratified by age, presence of dyslipidemia or hypertension, and by medication use." (PMID 28278265, 2017). "The participants with metabolic syndrome had significantly higher levels of LECT2 than those without metabolic syndrome." (PMID 28278265, 2017). "The optimal cutoff value for plasma LECT2 levels for the diagnosis of dyslipidemia was 16.5 ng/mL, suggesting that variation in plasma LECT2 levels, regardless of extremity, have clinical significance." (PMID 28278265, 2017). "Finally, we examined the relationship of LECT2 levels and VFA, with the presence of metabolic syndrome and dyslipidemia." (PMID 28278265, 2017). "First, due to the inherent limitations of a cross-sectional study design, no definite conclusions about causality between circulating LECT2 levels and the development of NAFLD or metabolic syndrome can be drawn." (PMID 28376109, 2017). "Participants with dyslipidemia also had higher levels of LECT2 than those without dyslipidemia." (PMID 28278265, 2017). "To demonstrate the clinical significance of measuring circulating LECT2, we performed ROC analysis to examine whether plasma LECT2 levels can be used to discriminate the participants with and without dyslipidemia." (PMID 28278265, 2017). "Indeed, the present study revealed that LECT2 levels are significantly higher in patients with metabolic syndrome compared to those without metabolic syndrome." (PMID 28376109, 2017). "Furthermore, the ROC analysis demonstrated that plasma LECT2 could be used as a biomarker to diagnose dyslipidemia in men, even though including LECT2 in addition to VFA in the regression model did not significantly increase the predictive value." (PMID 28278265, 2017). "The present study shows that circulating LECT2, which has been recently redefined as a hepatokine, is significantly higher in subjects with NAFLD and/or metabolic syndrome compared to those without NAFLD and metabolic syndrome." (PMID 28376109, 2017).
Hepatitis (9 papers, 2017 to 2024). Inflammation of the liver. "Previous research has shown that removing LECT2 during concanavalin A (ConA) -induced hepatitis can disturb the balance of Natural killer T cell (NKT cells) in the liver." (PMID 38881894, 2024). "In the pathogenesis of hepatitis, LECT2 is preferentially expressed in hepatocytes in its most basic molecular structure and enters the blood to participate in the inflammatory response." (PMID 34899846, 2021). "Additional research has uncovered how LECT2 controls the progression of hepatitis." (PMID 38881894, 2024). "LECT2-deficient (LECT2-/-) mice have exhibited a notably elevated proportion of liver NKT cells, which might contribute to the development of hepatitis." (PMID 38155961, 2023). "In the present study, we tested this hypothesis by investigating the significance of LECT2 gene expression in human liver tissues and the role of LECT2 in liver inflammation and the subsequent development of NASH in a mouse model of inflammation." (PMID 33436955, 2021). "LECT2 might regulate the homeostasis of NKT cells in the liver and might be involved in the pathogenesis of hepatitis." (PMID 35656863, 2022). "In LECT2-knockout mice, hepatitis gets more severe due to the increased number of NKT cells and their cytokine ligands, and therefore, the homeostasis of NKT cells in the liver is negatively regulated by LECT2." (PMID 31480179, 2019). "Lack of LECT2 (LECT2 knock-out) in mice resulted in more serious hepatitis induced by concanavalin A (in contrast to wild type mice)." (PMID 28591220, 2017).
non-alcoholic fatty liver disease (9 papers, 2019 to 2025). "Previous study showed that LECT2 expression is significantly elevated in nonalcoholic fatty liver disease, and LECT2 induces the development and progression of Nonalcoholic fatty liver disease through the STAT-1 signal pathway." (PMID 34899846, 2021). "It has been reported that Leukocyte cell-derived chemotaxin 2 (LECT2) is involved in immune reactions, severe liver injury, cancer, nonalcoholic steatohepatitis (NASH), nonalcoholic fatty liver disease (NAFLD) and so on." (PMID 34631799, 2021).
steatosis (8 papers, 2021 to 2025). Increased lipid within the cytoplasm of cells. "Elevated levels of fibroblast growth factor 21 (FGF21) and leukocyte cell-derived chemotaxin 2 (LECT2) have been correlated with steatosis severity and hepatic inflammation." (PMID 41011683, 2025). "On the other hand, circulating levels of the liver fat-associated hepatokines, LECT2, were closely correlated with the severity of NASH, including steatosis and inflammation." (PMID 37957316, 2024). "LECT2 is positively correlated with inflammation and steatosis, and the increase of LECT2 converts residual hepatic macrophages into M1-like phenotypes and promotes the development of hepatic inflammation." (PMID 36397950, 2022). "LECT2 expressions positively correlated with hepatic infammation and steatosis, it contributed to M1‐like macrophage phenotype and the M1/M2 ratio." (PMID 35656863, 2022). "In human liver biopsy samples, elevated LECT2 mRNA levels were positively correlated with body mass index (BMI) and increased in patients who have steatosis and inflammation in the liver." (PMID 33436955, 2021). "However, the role of LECT2 in the development of liver inflammation, which can bridge the gap from steatosis to fibrosis in the development of NASH, remains largely unclear." (PMID 33436955, 2021). "In this study, we and reference data (GSE31264 and GSE31455) showed that LECT2 mRNA is induced in cultured cells by HCV infection and significantly up-regulated in the liver tissue of patients with early-stage CHC compared with simple steatosis patients." (PMID 35676290, 2022).
Arthritis (5 papers, 2018 to 2024). Inflammation of a joint. "Further laboratory experiments are needed to investigate how LECT2 influences arthritis-related cytokines." (PMID 38881894, 2024). "In a mouse arthritis model, LECT2-/- mice exhibited more severe arthritic symptoms than the wild-type controls, which were indicated by LECT2-/- mice having more severe inflammation and erosion of cartilage and bone." (PMID 36969200, 2023). "In mice, LECT2 deficiency can cause severe arthritis, with reductions in the production of cytokines and chemokines, e.g., IL-1β, IL-6, TNF-α, and MCP-1, after exogenous LECT2 injection." (PMID 31310065, 2019). "Lect2 has a protective anti-inflammatory role in arthritis and in the liver Lect2 regulates the homeostasis of NKT cells and also the expression of IL-4 and IFN-γ." (PMID 30559928, 2018). "Furthermore, more recent research has revealed the link between LECT2 and the development of multiple immunological diseases such as sepsis, atherosclerosis, osteoporosis, arthritis, diabetes, atopic dermatitis, and non-alcoholic steatohepatitis (NASH)." (PMID 36969200, 2023). "It was also found that exogenous expression of LECT2 can alleviate arthritis symptoms in LECT2 knockout mice, which strongly suggests that LECT2 treatment might be a potential strategy against inflammatory arthritis such as RA." (PMID 36969200, 2023). "The severity of arthritis could be ameliorated by exogenous LECT2 protein." (PMID 35656863, 2022).
atherosclerosis (5 papers, 2017 to 2024). A disease characterized by the build-up of fatty material and calcium deposition in the arterial wall resulting in partial or complete occlusion of the arterial lumen. "LECT2, first identified as a chemokine for neutrophil migration is associated with immune diseases like non-alcoholic steatohepatitis (NASH), atherosclerosis (AS) and cholestatic liver disease." (PMID 39206203, 2024). "LECT2 has been found to be a potential diagnosis biomarker for atherosclerosis and correlated with the developmental stage of atherosclerosis." (PMID 36969200, 2023). "It was observed that at low and intermediate stages of atherosclerosis (stage I–IV on the 6-degree scale of H. Stary), the LECT2 antigen is visible and colocalizes around the nuclei of various cell types: macrophages, myocytes, and adipocytes." (PMID 38137613, 2023). "Nevertheless, it is worth tracing the relationship between inflammatory proteins and LECT2 in the development of metabolic and senile diseases such as atherosclerosis and diabetes." (PMID 38137613, 2023). "In the present study, we investigated the effects of LECT2 on the development of atherosclerosis in mice." (PMID 31310065, 2019). "We first measured atherosclerotic lesions in the aortas of Apoe–/– mice and found that LECT2 inhibited atherosclerosis, resulting in a 46% reduction in total plaque size." (PMID 31310065, 2019). "We proved that circulating LECT2 levels were significantly lower in atherosclerotic mice, suggesting that LECT2 has an inhibitory effect on atherosclerosis." (PMID 31310065, 2019). "In conclusion, we showed, for the first time, that LECT2 inhibits the development of atherosclerosis in a hypercholesterolemic mouse model, accompanied by reduced serum total cholesterol concentration and lower inflammatory responses." (PMID 31310065, 2019). "In summary, LECT2 inhibited the development of atherosclerosis in mice, accompanied by reduced serum total cholesterol concentration and lower inflammatory responses." (PMID 31310065, 2019). "The purpose of this study was to investigate the effects of LECT2 on atherosclerosis in Apoe-/- mice." (PMID 31310065, 2019). "We analyzed the levels of LECT2 in the AS and control groups to examine the relationship between serum LECT2 levels and atherosclerosis." (PMID 31310065, 2019). "The exact reason for this discrepancy between animal and human studies is not clear, and further study is needed to explore the relationship between LECT2 and atherosclerosis." (PMID 28376109, 2017). "In atherosclerosis (AS), LECT2 is highly expressed in diseased tissue and promotes phosphorylation of c-Jun N-terminal kinase (JNK) and the expression of intercellular cell adhesion molecule-1, inflammatory factors TNF-α, IL-1β, and MCP-1, inducing an inflammatory response." (PMID 39206203, 2024). "The researchers proposed the thesis that LECT2 levels not only indicate the onset of atherosclerosis but may also correlate with atherosclerotic plaque stability." (PMID 38137613, 2023). "However, there have been very limited studies to examine the clinical significance of circulating LECT2 levels in metabolic diseases including NAFLD and atherosclerosis in humans." (PMID 28376109, 2017). "LECT2 mitigated the expression and secretion of IL-1β, IL-8, TNF-α, and IL-1β dose-dependently in Apoe–/– mice fed with a Western diet, suggesting that LECT2 may inhibit atherosclerosis by alleviating inflammatory responses via Wnt/β-catenin signaling." (PMID 31310065, 2019). "Circulating LECT2 concentrations were increased in individuals with NAFLD and those with MetS, but not in those with atherosclerosis." (PMID 28376109, 2017).
diabetes (5 papers, 2021 to 2025). "The rationale for LECT2 being involved in the development of diabetes was the discovery that deletion of the Lect2 gene in mice improves peripheral glucose entry into tissues." (PMID 38137613, 2023). "Recently, accumulating evidence has indicated that LECT2 played crucial roles in various diseases, including diabetes, lung cancer, liver cancer, NAFLD, and so on." (PMID 34631799, 2021). "SR-A, which correlates with LECT2 in our case, however, is indirectly related to diabetes because it is a receptor that may bind advanced glycation products." (PMID 38137613, 2023).
liver cancer (5 papers, 2021 to 2024). An epithelial or non-epithelial malignant neoplasm that arises from the liver. "and H T Ong all discovered the ability of LECT2 to inhibit the migration and growth of liver cancer cells." (PMID 38881894, 2024). "LECT2 affects the evolution of liver cancer by altering the tumor phenotype and tumor microenvironment." (PMID 38881894, 2024). "Although many studies illustrated that LECT2 as a potential tumor suppressor in liver cancer, the detailed antitumor mechanism of LECT2 on HCC, especially hepatic cancer stem cells (CSCs) has remained largely unclear." (PMID 36055405, 2022). "Thus, LECT2 deletion modifies the tumour microenvironment and alters cancer phenotypes, suggesting that it is a promising immunotherapeutic target in liver cancer." (PMID 35574316, 2022). "Besides, the activities of c-MET and β-catenin signaling were not significantly and negatively correlated with the differentiation status and LECT2 expression in liver cancer cells." (PMID 36055405, 2022). "However, the antineoplastic mechanism of LECT2, especially its influence on hepatic cancer stem cells (CSCs), remains largely unknown." (PMID 36055405, 2022). "Interestingly, LECT2 seems to be a tumor suppressor in liver cancer, and it has been reported that LECT2 inhibits HCC progression mediated the blockade of c-MET signaling, tumoral angiogenesis, oncogenic behaviors of cancer cells and high-grade inflammation in HCC." (PMID 36055405, 2022). "In liver cancer, constitutively active β-catenin drives LECT2 upregulation in tumor tissues and HCC cells, and LECT2 is a direct target gene of β-catenin in liver." (PMID 36055405, 2022). "However, LECT2 expression is not up-regulated in some HCC specimens containing β-catenin-activating mutations, indicating that Wnt/β-catenin is not the only pathway that regulates LECT2 expression in liver cancer." (PMID 38881894, 2024).
liver disease (5 papers, 2021 to 2025). "In lipopolysaccharide or d-galactosamine induced acute liver injury animal model, LECT2 was found to be strongly associated with the prognosis of inflammatory liver disease." (PMID 34899846, 2021). "Several reports have shown that LECT2 may be a biomarker of survival prognosis for patients in various liver disease states." (PMID 34899846, 2021).
Abdominal obesity (4 papers, 2017 to 2025). Excessive fat around the stomach and abdomen. "Furthermore, plasma LECT2 levels had significant positive correlations with various metabolic risk factors including abdominal obesity, adverse lipid profiles, and low-grade systemic inflammatory status." (PMID 28376109, 2017). "The relationship between LECT2 and both NAFLD and MetS might be mediated by its association with abdominal obesity and lipid metabolism." (PMID 28376109, 2017).
bacterial sepsis (4 papers, 2017 to 2024). "It is reported that plasma LECT2 concentration of patients with bacterial sepsis is significantly lower than healthy humans and LECT2 expression is correlated with systemic inflammation." (PMID 31480179, 2019). "Earlier studies showed LECT2 improved protective immunity in bacterial sepsis." (PMID 28591220, 2017). "We drew a mechanism diagram by Figdraw to illustrate how LECT2 affects the development of related diseases, including HCC, liver fibrogenesis, bacterial sepsis, inflammatory response." (PMID 38881894, 2024).
non-alcoholic steatohepatitis (4 papers, 2021 to 2025). "Leukocyte Cell Derived Chemotaxin-2 (LECT2), which is elevated in patients with metabolic dysfunction-associated steatohepatitis (MASH), selectively promotes JNK phosphorylation in KCs, leading to liver inflammation." (PMID 40399593, 2025). "The aim of this study was to investigate the significance of LECT2 in the development of nonalcoholic steatohepatitis (NASH)." (PMID 33436955, 2021).
Sepsis (4 papers, 2016 to 2023). Sepsis is defined as life-threatening organ dysfunction caused by a dysregulated host response to infection. "Meanwhile, it turns out that plasma LECT2 concentrations in patients with sepsis were remarkably low and negatively correlated with the disease severity, which is rather the opposite of the expected effect." (PMID 38137613, 2023). "Several studies have revealed that LECT2 relieves both bacteria- and virus- induced sepsis in different mechanisms." (PMID 36969200, 2023). "All these results suggest that LECT2 is a potential drug for sepsis treatment." (PMID 36969200, 2023). "LECT2 concentrations correlated with the severity of systemic inflammation in patients with sepsis." (PMID 35656863, 2022). "We previously observed that LECT2 improves sepsis survival in mice by enhancing protective immunity but not by suppressing early inflammation." (PMID 27596364, 2016).
systemic amyloidosis (4 papers, 2022 to 2024). "Here, we developed the first microfluidic device designed to recapitulate the structures and shear forces present in the human kidney to study the aggregation of LECT2 and other proteins involved in systemic amyloidosis." (PMID 38537700, 2024). "Aggregation of leukocyte cell-derived chemotaxin 2 (LECT2) causes ALECT2, a systemic amyloidosis that affects the kidney and liver." (PMID 38537700, 2024). "LECT2, a subunit protein in amyloid fibrils, has been identified as a protein capable of inducing systemic amyloidosis in cases of nephrotic syndrome and azotemia." (PMID 38881894, 2024).
acute liver failure (3 papers, 2021 to 2024). Rapid deterioration of liver function causing encephalopathy and coagulopathy. "Previous studies evaluating serum LECT2 observed consistent results on whether LECT2 can be used to predict prognosis of acute liver failure, lower serum LECT2 is associated with better prognosis in adult acute liver failure patients." (PMID 34899846, 2021). "It was observed in patients with acute liver failure that the level of serum LECT2 was lower in the expired group, compared with the alive group (0.96 ± 0.8 ng/ml vs 12.9 ± 4.3 ng/ml p < 0.05)." (PMID 35656863, 2022). "When serum glutathione aminotransferase levels reached a peak, the serum LECT2 levels were lowest in patients with acute liver failure, and serum LECT2 levels increased when liver function returned to normal." (PMID 34899846, 2021). "From the prognostic point of view, serum LECT2 level may represent a good indicator for some acute critical liver‐related diseases, including acute fulminant hepatitis and acute liver failure." (PMID 35656863, 2022). "Serum LECT2 level may be a prognostic indicator for acute liver failure." (PMID 35656863, 2022).